ALK (ALK receptor tyrosine kinase)
Diseases named in the same sentence as ALK in open-access papers (continued):
Sharing a sentence is not in itself a finding about the gene and the disease.
tumor (continued). "It is plausible that triple combined blockade of GPX4, ALK, and activated bypass signals may be a potent therapeutic strategy for patients with ALK+ NSCLC to prevent the development of drug resistance, and lead to tumor eradication." (PMID 39369284, 2025). "A similar case involved a 3-year-old boy whose tumor could not be fully resected due to life-threatening hemorrhage, but an ALK fusion was identified after partial resection, and he was started on Lorlatinib." (PMID 41155159, 2025). "The combined inhibition of ALK plus inhibition of activated bypass signals plus inhibition of GPX4 may be a potent therapeutic strategy for patients with ALK+ NSCLC to prevent the development of resistance to ALK‐TKIs and lead to tumor eradication." (PMID 39369284, 2025). "Interestingly, subcutaneous tumor generation was observed in nude mice (7/8) injected with RDAA NIH3T3 cells but not those expressing ALK (0/8) or RNase1 (0/8) alone and NIH3T3 control (0/8)." (PMID 40246819, 2025). "The CT-based radiomics features were extracted separately from the gross tumor volume (GTV) and GTV incorporating peritumoral 3-, 6-, 9-, 12-, and 15-mm regions (GPTV3, GPTV6, GPTV9, GPTV12, and GPTV15), and screened the most relevant features to construct radiomics models to predict ALK (+)." (PMID 40083024, 2025). "ALK-negative or IgG4-mimicking tumours are particularly prone to misclassification." (PMID 40980125, 2025). "Therefore, any potential benefit seen with ALK inhibitors in these tumor-agnostic studies would most likely be due to the treatment itself, and not confounded by the presence of the ALK alteration." (PMID 40338218, 2025). "Their work further revealed that HIF2A, but not HIF1A, was essential for ALK+ ALCL tumor growth." (PMID 40734623, 2025). "However, tumours with EGFR mutations and ALK translocations showed no obvious benefit in second-line studies with single-agent checkpoint inhibitor therapy." (PMID 38610927, 2024). "The EMPOWER-Lung 1 trial compared the use of cemiplimab alone to the choice of chemotherapy made by the investigators in patients who were newly diagnosed with advanced NSCLC and tumor PD-L1 expression of at least 50%, along with no EGFR mutations or ALK or ROS1 fusions." (PMID 39027681, 2024). "This issue of overcoming ALK TKI resistance is exacerbated by the heterogeneous nature of cancer, where various resistance mechanisms may simultaneously manifest across different sites of the tumor." (PMID 38835344, 2024). "The disease onset and pathogenesis of the ALK fusion gene-positivity in our case are uncertain because we could not assess the pathology of the primary tumor." (PMID 39781173, 2024). "WNT-C59 specifically reduced EdU incorporation in ALK/MYCN tumor cells but not in MYCN tumor cells." (PMID 38451815, 2024). "In addition, an emerging technique is the use of circulating tumour DNA to explore dynamic ALK on‐ and off‐target resistance mechanisms not captured in a single site tissue biopsy, noting that in NSCLC, on‐ and off‐target mechanisms often co‐occur." (PMID 39188081, 2024). "The fact that miR-122-5p was barely detectable in cHL primary tumor samples and cell lines supports the hypothesis that it is released from non-tumor tissues—possibly the liver—like in pediatric ALK+ ALCL." (PMID 39769007, 2024). "In patients with NSCLC, pembrolizumab, an anti–PD-1 therapy, in the first-line setting showed superior efficacy compared with PDC in those patients who had PD-L1 expression in > = 50% of viable tumor cells without epidermal growth factor receptor (EGFR)/anaplastic lymphoma kinase (ALK) aberrations." (PMID 39448966, 2024).
tumor (continued). "Given its lack of efficacy and an immunosuppressive tumor microenvironment, alternative approaches may be needed to create responses to immunotherapy in ALK + NSCLCs." (PMID 38339280, 2024). "Likewise, YAP/TAZ is known to drive tumor proliferation and resistance in response to a variety of targeted therapies, including EGFR, Anaplastic Lymphoma Kinase (ALK), Mitogen-activated protein kinase (MEK), and Cyclin-dependent kinase 4/6 (CDK4/6) inhibitors." (PMID 38607003, 2024). "To evaluate whether FAK activity influences GSK3β, we treated ALK/MYCN tumor cells with or without the FAK inhibitor defactinib." (PMID 38451815, 2024). "Thus, survival analysis indicates that the presence of ALK protein expression alone, when detected immunohistochemically in over 50% of tumor cells, has prognostic value even in the absence of established molecular profiling of the tumors." (PMID 38339401, 2024). "Both screens identified ALK as the most effective combination target, altogether demonstrating that partial sensitivity to ALKi primary tumor cells was regulated by EGFR and PI3Kβ and could be effectively overcome by combined inhibition of ALK and EGFR or PI3Kβ." (PMID 36423211, 2023). "Clinical genomic evaluation of the tumor showed no alterations in the MYCN or ALK genes." (PMID 36980535, 2023). "The tumour cells were also positive for GATA3, E-cadherin, Pax-8, Succinate dehydrogenase B (SDHB) and Fumarate hydratase (FH), and negative for vimentin, Carbonic anhydrase 9 (CA9), CD10, P504s, CK20, TFE3, TFEB, HMB45, ALK and Forkhead box protein I1 (FOXI1)." (PMID 36816543, 2023). "When no targetable mutation is identified (NTRK, ALK, RET or BRAF) or the tumor is not sequenced, the antiangiogenic multi-targeted kinase inhibitors (aaMKIs) Sorafenib, Lenvatinib and Cabozantinib may be used." (PMID 37510219, 2023). "However, the characteristics of the tumour microenvironment (TME) and their prognostic values in ALK-rearranged NSCLC are unknown." (PMID 37371571, 2023). "ALK inhibitors bind to the ATP-binding pocket of the intracellular tyrosine kinase domain, and regulate their downstream signals such as the RAS, PI3K-AKT, JAK/STAT signaling cascades which are involved in tumor progression; attenuation of these cascades produces an antitumor effect." (PMID 36768562, 2023). "IHC testing was positive for anaplastic lymphoma kinase (ALK) protein (2+ staining intensity, 30% of tumor sample) and neurotrophic tyrosine receptor kinase TRK/NTRK (80%), suggesting that either ALK or TRK/NTRK1/2/3 could be a targetable driver in the tumor." (PMID 36619485, 2023). "Thus, a theory that ALK overexpression may be common in PNET tumors and simply has yet to be studied aligns with the known paucity of multiomic data for this tumor type." (PMID 36619485, 2023). "All the five tumours in this study had a typical immunophenotype characterized by diffuse positivity for CK7 and negativity for CD117, and were also positive for PAX-8, E-cadherin, FH and SDHB, but negative for vimentin, CD10, P504s, CA9, CK20, TFE3, TFEB, HMB45, and ALK." (PMID 36816543, 2023). "Hence, there is a lack of studies evaluating the TME of tumours with high PD-L1 expression in ALK-rearranged NSCLC and the impact of the TME on the prognosis of these patients." (PMID 37371571, 2023). "Additionally, most oncogene-driven NSCLC tumours initially responding to targeted therapies such as epidermal growth factor receptor (EGFR)-tyrosine kinase inhibitors (TKI) and anaplastic lymphoma kinase (ALK) inhibitors eventually progress over time as they acquire drug resistance." (PMID 37386452, 2023).
tumor (continued). "It has been determined that the PD-L1 expression varies during tumor progression due to communication between the tumor and the cells of immune system—the action of antitumor therapy, for example—against a background of the use of tyrosine kinase inhibitors that suppress the activity of EGFR or ALK." (PMID 36979782, 2023). "In addition, immune checkpoint inhibitors such as atezolizumab, cemiplimab, and nivolumab plus ipilimumab received FDA approval for treating patients with high PD-L1 expression and no EGFR or ALK genomic tumor aberrations." (PMID 37568193, 2023). "In ALK+ ALCL, however, impaired DNA repair pathways, particularly DNA mismatch repair, may represent a mechanism by which tumor cells initiate additional genetic lesions, considering that a subset of ALK+ALCL patients develop resistance against ALK-specific treatment approaches." (PMID 37810974, 2023). "Driver and drug-resistant mutations in primary tumours with LM included: EGFR L858R (10, 35.7%), EGFR 19del (6, 21.4%), EGFR L858R+MET (1, 3.6%), EGFR L858R+S768I (1, 3.6%), ALK (2, 7.1%), ROS1 (1, 3.6%), negative (5, 17.9%), and unknown (2, 7.1%)." (PMID 38269023, 2023). "Moreover, iruplinalkib showed robust antitumor effects in BALB/c nude mice xenograft models with ALK-/ROS1-positive tumors implanted subcutaneously, and the tumor suppressive effects in crizotinib-resistant model was significantly better than that of brigatinib." (PMID 37036582, 2023). "Immunohistochemical staining showed that the tumor cells were positive for thyroid transcription factor 1 (TTF-1) and CEA, but negative for prostate-specific antigen (PSA), Wilms tumor 1 (WT-1), p40, cytokeratin 5/6 (CK5/6), CK7, CK20 and anaplastic lymphoma kinase (ALK)." (PMID 38142271, 2023). "IMT is the tumor that most frequently overexpresses ALK protein, however, in addition to no expression of skeletal muscle markers Myo-D1, Myogenin and Myogenin, genetically, IMT usually shows ALK re-arrangement with many other molecular partners including TPM3, KIF5B, CARS, and THBS1." (PMID 36998041, 2023). "Secondly, in non-operable NSCLC patients with no EGFR or ALK genomic tumor aberrations, first-generation PD-1/PD-L1 inhibitors, either as monotherapy or in combination with platinum-containing combination chemotherapy, has become the standard of care first line treatment." (PMID 36650586, 2023). "Adults with stage IV/recurrent NSCLC without EGFR/ALK aberrations were randomized 1:1:1 to nivolumab plus ipilimumab, nivolumab alone, or chemotherapy (patients with tumor PD-L1 ≥ 1%), or nivolumab plus ipilimumab, nivolumab plus chemotherapy, or chemotherapy (patients with tumor PD-L1 < 1%)." (PMID 37548831, 2023). "Since ICOS engagement promotes ALK+ ALCL proliferation, it is tempting to speculate that by engaging its ligand (ICOS-L), tumor-specific ICOS subverts other critical co-stimulatory signals from immune cells, impairing cytotoxic response to tumor cells." (PMID 37810974, 2023). "The clinical outcome for ALK-rearranged NSCLC patients has dramatically changed in recent years thanks to the introduction in clinical practice of efficient ALK-i, which is able to significantly stop tumor growth and to guarantee patients long survival with high quality of life." (PMID 36230686, 2022). "No tumor with EGFR or ALK alterations demonstrated radiographical response or MPR." (PMID 36097216, 2022). "Interestingly, we found that tumor formation recapitulated the immune phenotypic diversity (including the less common CD8+ tumors), the histological pattern (large and small tumor cells) and the transcriptomic signature of ALK+ ALCL patient cells." (PMID 35246138, 2022). "Interestingly, FGFR1 phosphorylation was increased in the tumor tissues after TAE684 treatment, suggesting that the FGFR pathway might compensate for inhibition of ALK signaling." (PMID 35326668, 2022).
tumor (continued). "Here, we present a case report of a young never-smoker woman affected by an ALK-positive NSCLC tumor who presented an impressive resistance to sequential treatment with ALK TKIs mediated by YES1 and MYC amplifications in a complex context of EMT and high progressive chromosomal instability." (PMID 35199053, 2022). "However, it remains unclear how adaptive resistance to ALK inhibitors via HER3 activation and MET is related to the selection of epigenetically predefined subclones or true tumor cell plasticity." (PMID 35042943, 2022). "PD-1 and PD-L1 inhibitors are the mainstay of systemic treatment for aNSCLC in patients without therapeutically actionable tumor genomic aberrations, such as epidermal growth factor receptor (EGFR) mutations, anaplastic lymphoma kinase (ALK) translocations or ROS proto-oncogene 1 (ROS1) fusions." (PMID 36008722, 2022). "Similarly, mutations in NLRP1, ALK, and MAP3K1 were frequent among non-responders and tumor mutation count was significantly reduced in post-treatment samples." (PMID 36376989, 2022). "When considering results per ethnic subgroup, activating EGFR mutations were detected in 44%, 28% and 14% of non-squamous metastatic NSCLC tumours in Asian, black and white patients, respectively (p = 0.001) and ALK or ROS1 re-arrangement were detected in 22%, 3% and 17%, respectively (p = 0.2)." (PMID 36551542, 2022). "The reason for this is to provide the appropriate treatment by investigating whether the tumor expresses the epidermal growth factor receptor (EGFR), anaplastic lymphoma kinase (ALK), proto-oncogene 1 (ROS-1), proto-oncogene B-Raf (BRAF), and programmed death-ligand 1 (PD-L1)." (PMID 35329255, 2022). "ALK amplification also underlies resistance to ALK TKIs although it may not benefit tumor cells as it can trigger oncogenic stress and induce DNA damage especially upon discontinuation of an ALK TKI, resulting in tumor cell apoptosis and restoration of sensitivity to the inhibitor." (PMID 35211406, 2022). "Notably, abrogation of DNMT1 did not interfere with ALK levels or activity in ALKKO transgenic mice as indicated by similar pALK levels in ALK tumor cells and ALKKO thymocytes nor did it change pSTAT3 levels." (PMID 33310759, 2021). "Based on the promising efficacy, in 2021, the U.S. FDA granted tiragolumab BTD in combination with atezolizumab (Tecentriq) for the first‐line treatment of individuals with metastatic NSCLC whose tumors have PD‐L1 expression ≥50% and no EGFR or ALK genomic tumor aberrations." (PMID 34977873, 2021). "Two out of four studies described the use of anti-ALK medications in an ALK mutated NSCLC cohort, while the remaining two studies concerned a cohort of patients included regardless of molecular characteristics of the tumor." (PMID 34300130, 2021). "Additionally, increased autophagy in which cells break down obsolete constituents of their own cytoplasm as a way of generating additional energy for tumour growth and proliferation leads to crizotinib resistance in ALCL and NSCLC by allowing the cell to overcome the metabolic stress of the ALK TKI." (PMID 34885113, 2021). "Most ALK degraders have not shown in vivo anti‐tumor efficacy yet." (PMID 34766150, 2021). "In May 2020, treatment with nivolumab in combination with ipilimumab was approved for first-line treatment of patients with metastatic or recurrent NSCLC with no EGFR or ALK genomic tumor aberrations." (PMID 33677681, 2021). "However, most NSCLC patients are EGFR or ALK negative, and less than one-third of advanced lung tumors express PD-L1 in more than 50% of tumor cells." (PMID 34834454, 2021).
tumor (continued). "Immunohistochemical staining revealed the tumor cells to be positive moderately and diffusely for CD34 and focally for SMA and negative for Cam5.2, epithelial membrane antigen (EMA), desmin, calponin, TLE-1, CD99, Stat6, anaplastic lymphoma kinase (ALK, 1A4), SOX10, and S100 protein." (PMID 34256767, 2021). "To test whether ALKAL2‐driven NB was sensitive to ALK TKI treatment in vivo, we treated NB tumours arising in Rosa26_Alkal2;Th‐MYCN mice with lorlatinib (10 mg/kg body weight, 2× per day) for a period of 14 days and monitored tumour growth by ultrasound." (PMID 33411331, 2021). "In addition, we also performed immunohistochemistry for ALK on the tumor specimens, which were ALK negative (after we established a side-tumor control), We used the Olympus microscope, the type is BX53." (PMID 33879132, 2021). "Even tough expression of ALK and p-ALK is strongly correlated and others have reported similar findings regarding ALK expression in MCC tumor samples, it is possible that the differences between cell lines and the tumor data might be due to antibody cross-reactions." (PMID 34029351, 2021). "The one tumor showing ALK rearrangement clustered with the keratin-negative “control” group." (PMID 33742141, 2021). "However, the genetic landscape of this tumor is still not fully understood and treatment options are limited, especially in the majority of ALK-negative tumors." (PMID 34011083, 2021). "Our data suggest that the relationship between ALK and RET is complex, involving both transcriptional and post-translational regulation, likely reflecting a delicate interplay of developmental events in the sympathetic nervous system and tumor development that are currently not fully understood." (PMID 33921066, 2021). "Thus, the CheckMate026 study compared nivolumab at a dose of 3 mg/kg Q2W versus platinum-based CT in patients with stage IV NSCLC with PD-L1 expression >5% in tumor cells and without EGFR- and ALK-activating mutations, but this time the results was negative." (PMID 34104805, 2021). "Interestingly, in one patient an ALK gene fusion negative tumor had newly developed, contrary to the baseline tumor sample." (PMID 33572278, 2021). "The subsequent ALK rearrangement negative tumor cells may be related to clonal evolution under selective pressure by ALK TKIs." (PMID 32674491, 2020). "Furthermore, APC (p < 0.0001), ASXL1 (p < 0.0001), DNMT3B (p = 0.001), PARP4 (p = 0.002), MET (p = 0.01), TOP1 (p = 0.01), KDR (p = 0.01), SRC (p = 0.01), PAK1 (p = 0.015), ALK (p = 0.02), and MYC (p = 0.03) alterations were found to be more common in tumor samples from AO mCRC patients." (PMID 33194656, 2020). "Understanding the complexity and diversity of the immune context of the tumor microenvironment is essential to harness the immune system against these cancers, however, little is known about the heterogeneity of TIME due to the rarity of ALK-rearrangement in LCNEC." (PMID 33352665, 2020). "However, except from a handful of known genetic aberrations such as EGFR mutations and anaplastic lymphoma receptor tyrosine kinase (ALK) rearrangement, no subgroups of NSCLC are stratified for optimized treatment based on the molecular profile of the tumor." (PMID 33324562, 2020). "Using a highly sensitive, commercial CAPP-Seq assay, we demonstrated that ctDNA analyses prior to and early following ALK-TKI treatment initiation may predict clinical outcome and that longitudinal levels of tumor-derived SNVs in the plasma follow clinical response patterns." (PMID 32290439, 2020).